SIRT1 (sirtuin 1)
Diseases named in the same sentence as SIRT1 in open-access papers (continued):
Sharing a sentence is not in itself a finding about the gene and the disease.
Alzheimer disease (185 papers, 2008 to 2026). A progressive, neurodegenerative disease characterized by loss of function and death of nerve cells in several areas of the brain leading to loss of cognitive function such as memory and language. "It has been reported that SIRT1 activation has neuroprotective effects against age-associated neurological disorders, such as Alzheimer’s disease (AD), and is a therapeutic target for the optimal balance between anti-aging and anti-cancer activities." (PMID 40006059, 2025). "Decreased expression of sirtuin 1 (SirT1) has been implicated in Alzheimer’s disease (AD), and as we previously reported, is related to transcriptional repression by the major risk factor for sporadic AD, apolipoprotein E4 (ApoE4)." (PMID 40269061, 2025). "Dysfunctional SIRT1-dependent processes are associated with an increased risk of developing pathologies such as Parkinson’s, Hungtinton’s, and Alzheimer’s diseases." (PMID 39683482, 2024). "Decreased levels of BDNF, a key protein implicated in neuropsychiatric pathologies including Alzheimer’s disease, correlate with lower levels of SIRT1 in depressed and schizophrenic individuals, potentially implicating SIRT1 in psychiatric disorders." (PMID 39598406, 2024). "Various chronic diseases are associated with decreased expression of sirtuin 1 (lung cancer, systemic sclerosis), while others are associated with an increase in sirtuin 1 levels (chronic kidney disease, Alzheimer’s disease)." (PMID 37523061, 2023). "Previous reports had also associated the function of SIRT1 with miR-132- and miR-212-mediated regulation in the context of aging and Alzheimer’s Disease." (PMID 37298523, 2023). "Sirtuin 1 is highly expressed in the hippocampus and anterior cortex, which are associated with Alzheimer’s disease (AD) pathology." (PMID 37742223, 2023). "Both basic pathomechanisms underlying Alzheimer’s disease and some premises for stipulating a possible preventive role of some sirtuins, especially SIRT1 and SIRT3, protective against Alzheimer’s disease-related pathology, are discussed in this article." (PMID 36045741, 2022). "Overexpression of Sirt1 improved neuronal growth and survival, even in the presence of β-amyloid, a toxic peptide primarily associated with Alzheimer’s disease." (PMID 34828382, 2021). "Recent studies have indicated that SIRT1 is strongly implicated in neurodegenerative diseases, including Alzheimer’s disease as well as ischemic stroke and traumatic brain injury to the central nervous system." (PMID 33643568, 2021). "Reduction of SIRT1 levels was also demonstrated in parietal cortex in patients with Alzheimer’s disease, which was associated with the accumulation of Aβ and Tau, whereas activation of SIRT1 can suppress α-synuclein aggregation." (PMID 34206738, 2021). "An Alzheimer disease mice model proved that exist a balance concerning SIRT1 and AMPK signaling linked to inflammatory changes which are required for the RSV protective effects against Ab formation and cognitive plaque loss." (PMID 33336103, 2020). "Sirt1, one member in mammalian Sirtuin family, deacetylates protein and is associated closely with age-related diseases including Alzheimer’s disease." (PMID 30243024, 2018). "SIRT1/3 also plays the key roles in CR-related diseases such as age-associated disease, Parkinson's disease and Alzheimer's disease." (PMID 27659520, 2017). "It was also reported that the activation of neuronal SIRT1 was a possible mechanism underlying the protective effects of CR against the pathology of Alzheimer’s disease." (PMID 28225824, 2017). "The NAD+ levels were reported to decrease with age, and deficiencies of SIRT-1 might weaken mitophagy functions which were associated with age-related mitochondrial dysfunctional diseases including Alzheimer disease." (PMID 41021178, 2025).
Alzheimer disease (continued). "A deficiency in SIRT1 in the mouse brain has been observed to alter the distribution of site-specific phospho-tau in synaptosomes, thereby mediating a synaptic tauopathy in Alzheimer’s disease." (PMID 39766263, 2024). "Recent studies suggest a correlation between the reduced Sirt-1 expression with Alzheimer's diseases (AD) and depression, respectively, suggesting a possible pathogenic role of the altered Sirt-1 expression in neuronal degenerative diseases, such as AD and depression." (PMID 33834065, 2021). "In addition to its importance in physiological processes, SIRT1 has also been implicated in protection of neurons from degeneration in models of neurological diseases, such as traumatic brain injury and Alzheimer’s disease." (PMID 30416425, 2018). "Neurodegeneration such as Alzheimer’s disease is closely linked to the metabolic status and numerous reports have demonstrated that SIRT1 and autophagy are correlated with the balance between NAD+/NADH for maintaining metabolic homeostasis and cellular survival." (PMID 25247581, 2014). "For example, increased nuclear NAD biosynthesis and Sirt1 activation are linked to axonal protection, and hippocampus over expression of Sirt1 provides protection against neurodegeneration in a mouse model of Alzheimer's disease." (PMID 20020036, 2009). "Additionally, this review explores how SIRT1 depletion during aging contributes to the development of synaptic dysfunction, impaired cognitive function, and susceptibility to neurodegenerative diseases such as Alzheimer's disease (AD) and Parkinson's disease (PD)." (PMID 41934491, 2026). "Rashet, Abdi, and Barari elucidated the synergistic effect of aerobic training and resveratrol on the AMPK/PGC1-α/SIRT1 pathway in the hippocampus of rats afflicted with Alzheimer's Disease." (PMID 39959582, 2025). "The Aβ and tau expressions are regulated by Sirtuin 1 (SIRT1) in Alzheimer's Disease, which promotes the formation of Aβ aggregates, commonly referred to as senile plaques." (PMID 40231522, 2025). "Sirt1 is a prominent member of histone deacetylases, widely involved in oxidative stress, inflammation, cell metabolism, Alzheimer’s disease, and cardiovascular diseases." (PMID 40723307, 2025). "Despite these hurdles, the potential to achieve robust, disease-modifying efficacy justifies the increased effort and underscores the promise of dual GSK3β/SIRT1 targeting strategies in Alzheimer’s disease." (PMID 41031163, 2025). "The AMPK/SIRT1 pathway has been reported to have neuroprotective effects on neurons in neurological disorders such as Parkinson’s disease and Alzheimer’s disease." (PMID 39684318, 2024). "A number of studies have reported a correlation between reduced SIRT1 expression and the development of Alzheimer’s disease and depression." (PMID 39766263, 2024). "The fact that overexpression of SIRT1 is protective in mouse models of Alzheimer’s disease, amyotrophic lateral sclerosis (ALS), and Huntington’s disease further indicates a central role for SIRT1 in age-associated neurodegenerative disorders." (PMID 38452174, 2024). "Serum SIRT1 is able to cross the blood–brain barrier and is considered a promising potential serum biomarker for the early detection of Alzheimer’s disease." (PMID 39766263, 2024). "Accordingly, the decline in SIRT1 serum levels is a promising marker for early detection of endocrine and metabolic diseases, Alzheimer’s disease, cardiovascular disease, etc., and SIRT1 is reputedly a frailty-related biomarker." (PMID 38732001, 2024). "Of particular interest is the role of SIRT1 in suppressing neuronal amyloidogenesis, a key factor in the development of Alzheimer’s disease (AD)." (PMID 39598406, 2024).
Alzheimer disease (continued). "It has been consistently demonstrated that the levels and activity of Sirtuin 1 (SIRT1) in the cerebral cortex and hippocampus of patients with Alzheimer’s disease (AD) are diminished." (PMID 39744519, 2024). "ROC curve analysis demonstrated that SIRT1 was a promising biomarker to distinguish Alzheimer’s Disease patients from the mild cognitive impairment patients and the normal control group." (PMID 37742223, 2023). "A seminal study on the probiotic composition, SLAB51, unveiled its profound effect in bolstering SIRT1's expression and activity in the cerebrums of Alzheimer's Disease (AD) mice." (PMID 37962461, 2023). "Previous studies have shown that the reduction of SIRT1 level can lead to Alzheimer’s disease by promoting Aβ aggregation and tau hyperphosphorylation." (PMID 37742223, 2023). "The SIRT1 activators resveratrol and cilostazol have been shown to improve Alzheimer’s Disease Assessment Scale-Cognitive Subscale (ADAS-Cog) scores in AD patients." (PMID 37456463, 2023). "A functional link has been very recently established between the brain neuronal microRNAs miR-132 and miR-212 and their target-regulated protein Sirtuin 1 (Silent Information Regulator 1; in short, Sirt1) in the context of Alzheimer’s Disease." (PMID 37298523, 2023). "With respect to Alzheimer’s disease (AD), SIRT1 activation via resveratrol has been found to inhibit NF-κB and diminish amyloid-β’s (Aβ) neurotoxic effect in microglia." (PMID 37456463, 2023). "SIRT1 is ubiquitously expressed in the brain and regulates many processes that are altered in the pathogenesis of Alzheimer’s disease such as action potential propagation, neurodegeneration, and mitochondrial dysfunction." (PMID 36225477, 2022). "For instance, circRNA has been confirmed to mediate synaptic and amyloid precursor protein processing deficits through the circHDAC9/mi-138/sirtuin-1 pathway in Alzheimer’s disease." (PMID 36061613, 2022). "In mice, overexpression of SIRT1 led to decreased formation of beta-amyloid plaques characteristically seen in Alzheimer’s disease." (PMID 36225477, 2022). "Previous studies have indicated that SIRT1 protects against Alzheimer’s disease by interfering with the generation of β-amyloid peptides." (PMID 35517847, 2022). "Several microRNAs altered in Alzheimer’s disease target SIRT1, a class III HDAC and this affects learning and memory." (PMID 35842608, 2022). "By increasing the lysosome number and deacetylating lysosome-related proteins, SIRT1 also promotes β-amyloid peptide (Aβ) degradation in primary astrocytes, which is beneficial in Alzheimer’s disease." (PMID 35566069, 2022). "In Alzheimer’s disease models, SIRT1 directly interacted with and deacetylated TFEB at lysine residue 116 to enhanced lysosomal function and fAβ degradation, thus attenuating amyloid plaque deposition in APP/PS1 transgenic mice." (PMID 36111151, 2022). "Of note, neuronal SIRT1 has the potential to slow down Alzheimer’s disease during CR, and fasting enhances the SIRT1 mediated deacetylation of PPARγ, which activates PGC1α and regulates the rate-limiting enzyme for amyloid beta (Aβ) generation." (PMID 33806509, 2021). "DHM (200 mg/kg) protected rats from developing Alzheimer's disease via the up‐regulation of the AMPK/SIRT1 pathway to inhibit inflammatory responses and apoptosis of hippocampal cells and ameliorate cognitive function." (PMID 34676967, 2021). "Of interest, high expression of miR-132-3p in conjunction with low levels of SIRT1 was reported in lymphoblastoids of Alzheimer’s disease patients." (PMID 34769292, 2021). "SIRT1 also plays a role in autophagy, Alzheimer’s disease, ischemic injury and inflammatory gene expression." (PMID 33806509, 2021). "These pathways can lead to alleviating effects in neurodegenerative diseases, such as Alzheimer’s disease and amyotrophic lateral sclerosis via, for example, SIRT1-generated deacetylation (and activation) of PGC-1α." (PMID 34206738, 2021).
Alzheimer disease (continued). "It has been demonstrated that SIRT1 levels were decreased in neurodegenerative diseases, such as Alzheimer’s disease and Parkinson’s disease suggesting alleviating effects of SIRT1 activation-modulated pathway(s) in the treatment of neurodegenerative diseases." (PMID 34206738, 2021). "In fact, hypermethylation of the SIRT1 gene and significant decrease of SIRT1 expression has been observed in patients with Alzheimer disease." (PMID 33573081, 2021). "For example, hippocampal upregulation of miR-181 and related decrease of SIRT1 expression and, as a result, reduction of synaptic plasticity was demonstrated in a mouse model of Alzheimer’s disease." (PMID 34206738, 2021). "Previous studies of our group demonstrated that PBMT ameliorated dendritic atrophy via upregulation of BDNF and reduced Aβ levels by activating the PKA/SIRT1 signaling pathway in an Alzheimer's disease model." (PMID 33859781, 2021). "In other study, RSV increased the expression of genes encoding known antioxidants and anti-aging factors (SIRT1 and SIRT3) in Alzheimer's disease patients." (PMID 33336103, 2020). "It is also known that Sirt1 expression increases in Alzheimer’s disease and several other neurodegenerative disorders in order to give protection against rising neuronal stress." (PMID 32922128, 2020). "Recent reports have shown that SIRT1 upregulation can slow the progression of Alzheimer’s disease (AD) both in vitro and in vivo." (PMID 33269110, 2020). "For example, specifically promoting HDAC1 activity with pharmacological SIRT1 activators or by increasing HDAC1 function via genetic overexpression can reduce DNA damage in mouse models of Alzheimer's disease and ischemia." (PMID 32449313, 2020). "SIRT1 has reported neuroprotective activity in various neurodegenerative diseases, including Huntington's disease (HD), Alzheimer's disease (AD), and PD." (PMID 33204711, 2020). "Accumulating evidence demonstrated that Sirt1 plays an important role for neuroprotection in several models of neurodegenerative diseases, such as Alzheimer’s disease (AD), while the level of hippocampal Sirt1 were significantly decreased in patients with AD." (PMID 32218719, 2020). "Previously, Sirt1 has been shown to exhibit neuroprotective properties in an array of neurological disorders, such as Alzheimer’s disease, Parkinson’s disease, and Huntington’s disease." (PMID 31428461, 2019). "The aim of the present study was to understand the possible role of the Dihydromyricetin (DHM) in Alzheimer’s disease (AD) rat model through regulation of the AMPK/SIRT1 signaling pathway." (PMID 30498091, 2019). "Studies have demonstrated that in an animal model of Alzheimer’s disease, the β-amyloid protein (Aβ) content in the brain is negatively correlated with the SIRT1 content in the same region." (PMID 31164908, 2019). "For instance, the overexpression of SIRT1 in the hippocampus of p25 transgenic mice, which exhibit massive degeneration of the forebrain with features of Alzheimer’s disease, significantly protects the mouse brain from neurodegeneration." (PMID 31492861, 2019). "In our earlier study with sirtuin in Alzheimer’s disease, which is another of the most common neurodegenerative diseases, we found the downregulation of SIRT1 in serum compared with mild cognitive impairment as well as the control group." (PMID 31244600, 2019). "SIRT1 attenuates the neurotoxic effects of Aβ in Alzheimer’s disease by inhibiting NF-κB signaling in microglia." (PMID 31164908, 2019). "Sirtuin 1 (SIRT1) enzyme regulates major cell activities, and its activation offers lucrative therapeutic potentials for aging diseases including Alzheimer's disease (AD)." (PMID 31217784, 2019).
Alzheimer disease (continued). "Increased expression of miR-34c and decreased expression of SIRT1 were detected in mice with age-associated memory impairment and APPPS-21 mice, which are a model of amyloid pathology linked to Alzheimer’s disease (AD)." (PMID 30416425, 2018). "In vivo, A03 treatment increased SirT1 levels in the hippocampus of 5XFAD-ApoE4 (E4FAD) Alzheimer’s disease (AD) model mice and elicited cognitive improvement while inducing no observed toxicity." (PMID 30514854, 2018). "For example, SIRT1 overexpression has proven beneficial in models of Alzheimer disease, Huntington disease, and PD." (PMID 28257421, 2017). "In post-mortem brain tissue obtained from patients with Parkinson’s disease, Parkinson’s disease with dementia, dementia with Lewy bodies and Alzheimer’s disease, the activity of SIRT1 was observed to be down-regulated." (PMID 28578695, 2017). "The protective effect of caloric restriction with increased SIRT1 expression on Alzheimer's disease was first reported in 2006." (PMID 26904696, 2016). "SIRT1 has its protective roles in different neurodegenerative diseases, such as Alzheimer's disease and Parkinson's disease." (PMID 27203679, 2016). "Sirt1 activity in p25-overexpression mice, a model of Alzheimer’s disease and tauopathies, was shown to protect against neurodegeneration." (PMID 26219988, 2015). "SIRT1 can protect neurons from oxidative stress and neurotoxic insults in several models for Alzheimer’s disease, ALS, and Wallerian degeneration." (PMID 26426123, 2015). "In human, a post-mortem study showed a SIRT1 expression decrease in brain of Alzheimer disease patients, a chronic neurodegenerative pathology where OS is also present." (PMID 24586272, 2014). "A role for resveratrol and SIRT1 in neuroprotection has been suggested in other neurodegenerative processes besides demyelinating disease, including models of Alzheimer’s disease, amyotrophic lateral sclerosis, and axotomized dorsal root ganglion cells." (PMID 24383546, 2014). "Neuroprotective effects of SIRT1 have been reported in Huntington’s disease, Parkinson’s disease, Alzheimer’s disease, and spinal and bulbar muscular atrophy." (PMID 25167838, 2014). "Three other miRNAs have been found to supress SIRT1, namely miR-181c, miR-34, and miR-132, all of which show consistent altered expression in Alzheimer's disease brain." (PMID 24133413, 2013). "Sirt1 was shown to protect neurons against neurodegeneration in Alzheimer's disease and amyotrophic lateral sclerosis." (PMID 21390294, 2011). "SIRT1 overexpression similarly has been shown to confer neuroprotection in a rodent model of Alzheimer’s disease." (PMID 20335973, 2010). "For example, the overexpression of SIRT1 prevents neuronal death in tissue culture models of Alzheimer's disease, amyotropic lateral sclerosis, and polyglutamine toxicity and reduces hippocampal degeneration in a mouse model of Alzheimer's disease toxicity." (PMID 19116652, 2008). "Research indicates that RSV may exert neuroprotective effects in Alzheimer’s disease models through Sirt1 signal transduction." (PMID 39439517, 2024). "Moreover, neuronal mitochondrial biogenesis is impaired in NDDs such as Alzheimer’s disease (AD) and Parkinson’s disease (PD), and SIRT1 plays a central role in mitochondrial biogenesis regulation in these diseases." (PMID 39273653, 2024). "Furthermore, a reduction in the level of sirtuins, especially SIRT1, in neurodegenerative diseases (such as Parkinson’s disease or Alzheimer’s disease) was also more commonly observed in women than in men." (PMID 39335541, 2024). "In addition, SIRT1 was estimated to perform well in the diagnosis of Alzheimer’s Disease ([AUC] = 0.742)." (PMID 37742223, 2023). "Recently, SIRT1 was found to play an important role in Alzheimer's disease and Parkinson's disease." (PMID 36238648, 2022). "Furthermore, upon autopsy of human brains with Alzheimer’s disease, expression of SIRT1 and SIRT3 were decreased." (PMID 36225477, 2022).